SIRT1 (sirtuin 1)
Diseases named in the same sentence as SIRT1 in open-access papers (continued):
Sharing a sentence is not in itself a finding about the gene and the disease.
sarcoma (13 papers, 2012 to 2024). A usually aggressive malignant neoplasm of the soft tissue or bone. "In order to reveal the association between the expressions of five TcoF-related genes (LMO2, MAML3, MTF2, RBPMS, and SIRT1) in the risk model and immune cell infiltration, the data on sarcoma from the TIMER database were collected." (PMID 35734428, 2022). "Mutations of each gene (LMO2, MAML3, MTF2, RBPMS, and SIRT1) in sarcoma were 6, 7, 6, 3, and 5%, respectively, with the most common changes in the mRNA expression." (PMID 35734428, 2022). "In this study, the pro-proliferative role of SIRT1 and β-catenin in sarcoma is supported by significant correlations of their expression with higher mitotic count and Ki67 index." (PMID 24019980, 2013). "Our result also has shown that the expression of DBC1 and SIRT1 are positively correlated and both closely related with poor prognosis of sarcoma." (PMID 24019980, 2013). "Multivariate analysis revealed the expression of SIRT1 as an independent prognostic indicator for overall survival and event-free survival of sarcoma patients." (PMID 24019980, 2013). "To prove whether sirtuins are essential to sarcoma cell growth, we knocked down SIRT1 and SIRT2 in RD cells using a cocktail of four different siRNAs for each sirtuin to avoid off-target effects, and followed cell proliferation for 120 h." (PMID 25341037, 2014). "We quantified SIRT1 and SIRT2 mRNA expression in 12 fresh frozen synovial sarcomas (SS), 7 sarcoma cell lines and 4 primary human mesenchymal cells (diploid fibroblasts and mesenchymal stem cells) using QRT-PCR." (PMID 25341037, 2014). "Using siRNA to knock down SIRT1 and SIRT2 expression, we demonstrated that SIRT1 and SIRT2 expression is crucial for the survival of sarcoma cells." (PMID 25341037, 2014). "We found that the pharmacological inhibition of SIRT1 and SIRT2 with tenovin-6 effectively inhibited the proliferation of seven pediatric sarcoma cell lines at concentrations between 2 and 5 μM." (PMID 25341037, 2014). "Our results show sarcoma subtype-specific patterns of TOP2A and SIRT1 expression." (PMID 34638362, 2021). "When considering the extensive studies and important role of SIRT1 and DBC1 in human carcinomas, there is a rationale that SIRT1 and DBC1 also could be involved in the pathogenesis of sarcoma." (PMID 24019980, 2013). "The mean Ki67 index of SIRT1-expressing sarcomas was eight times higher than SIRT1-negative sarcomas (mean ± standard error: 434 ± 85 versus 59 ± 24, 2-tailed t-test; P = 0.006)." (PMID 24019980, 2013). "In conclusion, this study demonstrates that SIRT1- and DBC1-related pathways may be involved in the progression of soft-tissue sarcomas and can be used as clinically significant prognostic indicators for sarcoma patients." (PMID 24019980, 2013). "Moreover, the SIRT1- and DBC1-related pathways could be new therapeutic targets for the treatment of sarcomas." (PMID 24019980, 2013). "In addition, SIRT1, β-catenin, and DBC1-related pathways may be involved in the progression of sarcomas and could be new therapeutic targets for the treatment of soft-tissue sarcomas." (PMID 24019980, 2013). "Therefore, further study focused on specific types of soft-tissue sarcoma is needed to understand the exact role of SIRT1- and DBC1-related pathways in sarcomas and determine the best use of them as therapeutic targets for the treatment of specific types of soft-tissue sarcoma." (PMID 24019980, 2013).
age-related hearing loss (12 papers, 2017 to 2025). "A search of PUBMED for the keywords “SIRT1,” “hearing loss,” “cochlea,” “presbycusis” and “age-related hearing loss,” showed that there were less than 50 studies related to SIRT1 and hearing until now, of which 14 studies were related to ARHL." (PMID 36204138, 2022). "SIRT1 plays a protective role to prevent hair cell death in age-related hearing loss." (PMID 30692914, 2018). "It’s also reported that the SIRT1/PGC-1α signaling pathway is involved in age-related hearing loss, and the downregulated SIRT/PGC-1α increases the incidence of age-related hearing loss via promoting the apoptosis of cochlear hair cells." (PMID 35620603, 2022). "Reduced expression of SIRT1- PGC-1α may impair the synthesis and respiratory function of mitochondria, thereby causing neuronal degeneration and cell apoptosis, thus leading to presbycusis." (PMID 29937713, 2018). "Conversely, the down-regulation of miR-29b and the up-regulation of Sirt1/Pgc-1α can inhibit the apoptosis of cochlear hair cells, while the down-regulation of Sirt1/Pgc-1α may increase the incidence of presbycusis by promoting the apoptosis of cochlear hair cells." (PMID 40226444, 2025). "The expression of SIRT1 in the inner ear cells of aged C57BL/6 mice was significantly downregulated, and the expression of SIRT1 was found to positively regulate apoptosis in HEI-OC1 cells, indicating that SIRT1 is related to the onset of presbycusis." (PMID 39531447, 2024).
alcoholic fatty liver disease (12 papers, 2012 to 2025). Lipid infiltration of the hepatic parenchymal cells that is due to alcohol abuse. "The result showed the protective effect of LF against non-alcoholic fatty liver disease via activating the AMPK/SIRT1 and Nrf2/HO-1 pathway activation." (PMID 40862425, 2025). "Chronic consumption of ethanol causes an inhibition of the hepatic SIRT1-AMPK signalling system; resveratrol works by reversing this action and preventing the development of alcoholic fatty liver disease." (PMID 33805795, 2021). "The SIRT1/SIRT3-FOXO3a pathway is activated by Liraglutide to promote autophagy in non-alcohol fatty liver disease." (PMID 29896416, 2018). "Involvement of the adiponectin-Sirt1-AMPK pathway in the RGZ-mediated protection against alcoholic fatty liver disease was demonstrated in ethanol-treated mice." (PMID 25133775, 2014). "Adiponectin is an adipocyte-derived adipokines and can protect against alcoholic fatty liver disease via the activation of the SIRT1- (sirtuin 1-) AMPK pathway." (PMID 22536284, 2012). "Focusing attention on the molecular mechanisms related to the role of resveratrol in alcoholic fatty liver disease—the activation of SIRT1 (sirtuin 1) and AMPK (AMP-activated kinase)—two critical signalling molecules that regulate the metabolic pathways of liver lipids were highlighted." (PMID 33805795, 2021). "In a mouse model of alcoholic fatty liver disease, RGZ treatment activated the hepatic Sirt1-AMPK signaling pathway, resulting in increased fatty acid oxidation and inhibited lipogenesis in the liver." (PMID 25133775, 2014). "Sirtuin 1 (SIRT1), the SIRT1/NF-κB axis, SIRT3, and SIRT4 play a major role in regulating hepatic lipid metabolism, controlling oxidative stress, and mediating chronic inflammation in NAFLD and alcoholic fatty liver disease." (PMID 35203484, 2022). "Considering the already well-known alleviating bioactivity of A. cinnamomea for the alcoholic steatohepatitis (ASH), we propose that Ant can be beneficial to NAFLD, and that the AMPK/Sirt1/PPARγ/SREBP-1c pathways may be involved in such alleviations." (PMID 31935815, 2020).
esophageal squamous cell carcinoma (12 papers, 2014 to 2025). Esophageal squamous cell carcinoma (ESCC) is a type of esophageal carcinoma (EC) that can affect any part of the esophagus, but is usually located in the upper or middle third. "Several studies reported that the expression of SIRT1 was associated with the clinical features of patients with esophageal squamous cell carcinoma (ESCC), but the function remains inconsistent." (PMID 35350833, 2022). "Numerous investigations have analyzed tissues and EC cell lines from EC patients, particularly those with esophageal squamous cell carcinoma (ESCC), revealing that high SIRT1 expression is associated with advanced TNM stage, poor prognosis, lymph node metastasis, inferior overall survival (Ma MC." (PMID 40567502, 2025). "Long non‐coding RNA HOXC‐AS1 exerts its oncogenic effects in esophageal squamous cell carcinoma by interaction with IGF2BP2 to stabilize SIRT1 mRNA expression." (PMID 36510377, 2023). "The aim of the present study was to clarify the prognostic role of SIRT1 in patients with esophageal squamous cell carcinoma (ESCC) and evaluate the effect of SIRT1 inhibitor in vitro." (PMID 29636061, 2018). "In summary, early increases in ADC may facilitate the predication of early CRT response in patients with esophageal squamous cell carcinoma (ESCC), which may be attributed to the different correlation between ADC changes and SIRT1 expression." (PMID 31684999, 2019). "This research investigated the prevalence of SIRT1 protein expression and its prognostic influence with the aim of validating its potential role in lymphangiogenesis and lymphovascular invasion (LVI) in pN0 esophageal squamous cell carcinoma (ESCC)." (PMID 25922660, 2014).
kidney injury (12 papers, 2014 to 2026). Trauma to the kidney. "In numerous kidney injury animal models, evidence has been shown that activating the SIRT1/Nrf2/HO-1 pathway can counteract oxidative stress and apoptosis; hence, the SIRT1/Nrf2/HO-1 cascade is an essential cellular defense mechanism against ROS and apoptosis." (PMID 37237729, 2023). "Promotion of mitochondrial biogenesis and PGC-1α activation by activators of SIRT1 has also been proposed as repair mechanisms after I/R-induced kidney injury." (PMID 32932720, 2020). "We examined molecular and cellular responses in inducible Sirt1 knockout (Sirt1−/−) mice and wild type littermates (Sirt1+/+) in lipopolysaccharide (LPS)-induced kidney injury." (PMID 24896770, 2014). "Additionally, it has been revealed that CYP2J2-produced epoxyeicosatrienoic acids protect against ischemia/reperfusion-induced kidney injuries by activating the SIRT1-FoxO3a signaling pathway." (PMID 35386302, 2022). "Treatment with SRT1720, an SIRT1 activator, restored renal ATP levels through reduction of mitochondrial mass, nitrosative stress, and inflammation, leading to attenuation of I/R-induced kidney injury." (PMID 32932720, 2020). "Moreover, it can also control circadian clocks and mitochondrial biogenesis, suggesting that SIRT1 is an important age-related protective factor against I/R-induced kidney injury." (PMID 28425936, 2017). "Moreover, irisin, via the SIRT1/Nrf2 pathway,attenuates acute kidney injury in septic mice." (PMID 38566123, 2024). "Both Sirt1 and PGC‐1α agonists can be used as effective antagonists of ferroptosis and targets for the treatment of CaOx‐induced kidney injury." (PMID 39498889, 2024). "After induction of kidney injury, serum urea and creatinine, urinary albumin, kidney MDA and TGF-β1 levels increased in rats with both previous exercise and no previous exercise, while GFR, and kidney TAC and SIRT1 levels significantly decreased." (PMID 35236328, 2022).
pulmonary hypertension (12 papers, 2014 to 2025). Increased pressure within the pulmonary circulation due to lung or heart disorder. "It was proven, in knockout mice, that deficiency in SIRT1 gene aggravates chronic hypoxia-induced pulmonary hypertension." (PMID 32566097, 2020). "However, our study focused on whether SIRT1 was involved in resveratrol-mediated prevention of pulmonary arterial hypertension and the underlying mechanism." (PMID 26273643, 2015). "SIRT1 is reduced by growth factors in human pulmonary artery smooth muscle cells in vitro and in a monocrotaline-induced pulmonary hypertension in rats, whereas SIRT1 inhibits smooth muscle proliferation." (PMID 40554265, 2025). "Among the histone-modifying enzymes, the NAD-dependent deacetylase SIRT1 (sirtuin 1) is a particularly well-known modulator of pulmonary hypertension." (PMID 37398657, 2023). "When it comes to pulmonary hypertension, Sirt1 up-regulation initiates the Akt signaling pathway to facilitate hypoxia-elicited proliferation in human pulmonary artery endothelial cells and curb their apoptosis." (PMID 37142272, 2023). "Resveratrol inhibits pulmonary artery smooth muscle cell proliferation and right ventricular remodeling in pulmonary hypertension by regulating Nrf2, SIRT1 pathway and HIF-1α expression." (PMID 37779908, 2023). "Acetylation and deacetylation balance owing to Sirt1 inactivation alters pulmonary hypertension pathogenesis." (PMID 37142272, 2023). "All these phenomena revealed that miR-663b modulated the AMPK/Sirt1 signaling pathway to exert a function in pulmonary hypertension development." (PMID 37142272, 2023). "For example, although SIRT1 expression in immune cells can lessen unregulated cellular growth, resveratrol—a sirtuin 1 agonist—decreases pulmonary hypertension in the rat monocrotaline model, and others, in a pulmonary artery smooth muscle cell-specific manner." (PMID 30081463, 2018). "In pulmonary arterial hypertension (PAH), miR-663 b in M1-Exos inhibits the AMPK/Sirt1 signalling pathway in pulmonary artery smooth muscle cells (PASMCs), inducing proliferation, inflammation, oxidative stress, and migration, thereby worsening the disease condition." (PMID 40371346, 2025).
retinal degeneration (12 papers, 2016 to 2025). Degeneration of the retina. "In our in vivo model of PD, we confirmed that miR-384-5p acts as a negative regulator of SIRT1 expression in the retina, reinforcing its role in PD-related retinal degeneration." (PMID 41315232, 2025). "Our findings corroborate that PIC-OCT protects photoreceptors by modulating the SIRT1/PARP1 axis in models of retinal degeneration." (PMID 38397799, 2024). "Sirtuin 1 protein is found in the outer nuclear layer and is secreted in the early stages of retinal degeneration, aiding the repair process." (PMID 37371967, 2023). "Few studies have reported the significant role of SIRT1 cataracts and retinal degeneration development." (PMID 35629418, 2022). "In rd10 mice the expression of SIRT1 was found in the outer nuclear layer and its expression pattern correlated with the beginning of retinal degeneration in these mice." (PMID 34834350, 2021). "However, the results were not consistent with the previous studies that proved the promotion of autophagy and the Nrf2-PGC1- Sirt1 signaling pathway accompanied by the attenuation of ROS in retinal degeneration." (PMID 34356358, 2021). "Thus, it was concluded that SIRT1 is activated in the early stages of retinal degeneration to contribute to reparative processes." (PMID 34834350, 2021). "In fact, SIRT1 might be involved in retinal degeneration via modulating cell senescence, DNA damage repair, and apoptosis." (PMID 30037017, 2018). "Based on our observations we hypothesize that repressed AMPK / SIRT1 / PGC-1α pathway could affect mitochondrial biogenesis and remodeling, causing increased ROS production, leading to RPE and retinal degeneration in AMD." (PMID 27998274, 2016). "SIRT1, which could exist effective biological effects through antioxidant and antiapoptosis mechanisms, has been shown to be downregulated in various animal models of retinal degeneration." (PMID 38638334, 2023). "The role of SIRT1, an NAD+-dependent histone deacetylase, in the progress and protection of retinal degeneration has been reported in great details in several disease models." (PMID 32070320, 2020). "However, the slight upregulation of SIRT1 could not make a significant difference in the outcome of retinal degeneration in the MNU-induced RP rats." (PMID 37388281, 2023).
squamous cell carcinoma (12 papers, 2012 to 2025). A carcinoma arising from squamous epithelial cells. "SIRT1 expression levels were significantly higher in adenocarcinomas (ADC) than in squamous cell carcinomas (SCC) (P = 0.033)." (PMID 25915617, 2015). "Stronger nuclear SIRT1 staining was observed in adenocarcinomas than in squamous cell carcinomas (P=0.033)." (PMID 25915617, 2015). "Lin and Peng found that SIRT1 is expressed during the NSCLC progress, especially in patients with squamous cell carcinomas, and might serve as a prognostic indicator for NSCLC." (PMID 32267139, 2020). "Conversely, over-expression of SIRT1 was frequently observed in all kinds of non-melanoma skin cancers, including squamous cell carcinoma, basal cell carcinoma, Bowen's disease, and actinic keratosis 41,42." (PMID 32398958, 2020).